TXNRD2 (thioredoxin reductase 2)
Diseases named in the same sentence as TXNRD2 in open-access papers (continued):
Sharing a sentence is not in itself a finding about the gene and the disease.
colon cancer (2 papers, 2012 to 2025). "SIRT5 demalonylates K179 of SDHA, downregulating its activity, leading to succinate accumulation and activation of the ROS scavenging enzyme thioredoxin reductase 2 (TrxR2), causing colon cancer cell resistance to rituximab." (PMID 39979670, 2025). "Five SNPs in TXNRD2 and one in SelS, SeP15, and SelW1 interacted with estrogen to modify colon cancer risk; one SNP in SelW1 interacted with estrogen to alter rectal cancer risk." (PMID 22615972, 2012). "Two SNPs in TXNRD2 interacted significant with cigarette smoking for colon cancer where those who smoked were at greater risk with the variant allele; associations were not statistically significant after adjustment for multiple comparisons." (PMID 22615972, 2012). "TXNRD1, TXNRD2, TXNRD3, and SelN1 interacted with BMI to alter risk of colon cancer and TXNRD1 interacted with BMI to statistically alter risk associated with rectal cancer." (PMID 22615972, 2012). "Although three SNPs in TXNRD1, TXNRD2 and SelN1 were associated with colon cancer, none remained statistically significant after adjustment for multiple comparisons as indicated by the pACT." (PMID 22615972, 2012). "Two SNPs in TXNRD1 and four SNPs in TXNRD2 interacted with aspirin/NSAID to influence colon cancer; one SNP in TXNRD1, two SNPs in TXNRD2, and one SNP in TXNRD3 interacted with aspirin/NSAIDs to influence rectal cancer." (PMID 22615972, 2012).
colorectal cancer (2 papers, 2012 to 2024). A primary or metastatic malignant neoplasm that affects the colon or rectum. "We evaluated the association between genetic variation in TXNRD1, TXNRD2, TXNRD3, C11orf31 (SelH), SelW, SelN1, SelS, SepX, and SeP15 with colorectal cancer risk." (PMID 22615972, 2012).
coronary artery disease (2 papers, 2018 to 2025). "Due to cardiomyocytes being highly dependent on mitochondrial energy metabolism, TXNRD2 may play a key role in the progression of heart failure in patients with ischemic heart disease, hereditary cardiomyopathy, or other diseases." (PMID 40726908, 2025).
heart failure (2 papers, 2020 to 2025). Inability of the heart to pump blood at an adequate rate to meet tissue metabolic requirements. "al. showed, in a knockout model of Txnrd2, myocardium contractile and metabolic function was induced, suggesting Txnrd2 may be a modifier of heart failure during aging." (PMID 32210049, 2020).
lung carcinoma (2 papers, 2019 to 2024). "In another study, serum selenium levels were determined in 95 patients with lung cancer and the genotypes of four selenoprotein genes (GPX1, GPX4, TXNRD2, and SEP15) were determined, demonstrating that a selenium level less than 60 μg·L−1 is associated with a higher risk of lung cancer." (PMID 30759767, 2019).
rectal cancer (2 papers, 2012 to 2019). A primary or metastatic malignant neoplasm that affects the rectum. "In this paper we evaluate associations between genetic polymorphism in TXNRD1, TXNRD2, TXNRD3, C11orf31 (i.e. SelH), SelW, SelN1, SelS, SepX, and SeP15 and colon and rectal cancer." (PMID 22615972, 2012). "In these data TXNRD1, TXNRD2, TNXRD3, SepX1, and SelN1, and SeP15 also were associated with survival after diagnosis with colon or rectal cancer." (PMID 22615972, 2012). "TXNRD2 (3 SNPs), TXNRD3 (3 SNPs), SelN1 (3 SNPs), and SepX1 (1 SNP) were associated with rectal cancer." (PMID 22615972, 2012). "We observed numerous statistically significant interactions between candidate genes, TXNRD2, SelS, SeP15, and SelW1 and estrogen status for both colon and rectal cancer." (PMID 22615972, 2012).
aneurysm (1 paper, 2018). Bulging or ballooning in an area of an artery secondary to arterial wall weakening. "The risk of AAA was influenced by specific two-locus effects between the SEPP1, SELENOS, and TXNRD2 genes, which resulted in 50% reduced susceptibility to aneurysm development." (PMID 30188935, 2018).
aortic valve stenosis (1 paper, 2016). Aortic valve stenosis (AVS) is a condition characterized by narrowing of the heart's aortic valve opening. "Chromosome micro-deletions (del22q11) involving TXNRD2 have also been associated with various congenital heart defects including aortic valve stenosis." (PMID 27152866, 2016).
diabetes (1 paper, 2025). "Several authors have investigated polymorphisms in the TXNRD2 and TXNIP and DN, as well as other complications related to diabetes." (PMID 40076459, 2025).
diabetic kidney disease (1 paper, 2025). Progressive kidney disorder caused by vascular damage to the glomerular capillaries, in patients with diabetes mellitus. "Three other polymorphisms in TXNRD2 were found to be associated with diabetic kidney disease in Greek patients with T2DM." (PMID 40076459, 2025).
glioma (1 paper, 2024). A benign or malignant brain and spinal cord tumor that arises from glial cells (astrocytes, oligodendrocytes, ependymal cells). "Other mitochondrial oxidative-stress-related genes including CTSL, TXNRD2, NUDT1, STOX1, and CYP2E1 have been reported differentially expressed with potential prediction accuracy of glioma." (PMID 39012280, 2024).
gouty arthritis (1 paper, 2022). "LXA4 also subverted the increase in Nrf2 and Klf9 and depression of TXNRD2 in gouty arthritis rats, which is consistent with in vitro data." (PMID 36569930, 2022).
Hyperglycemia (1 paper, 2013). An increased concentration of glucose in the blood. "Interestingly in contrast to HUVEC, the gene expression of ROS clearance enzymes, SOD1, GPX1, TXNRD1, TXNRD2, and PRDX1 were upregulated in HMVEC under hyperglycemia." (PMID 24093550, 2013). "Not much detail is available in literature for hyperglycemia-induced gene expression of NFE2L2, TXNRD1, TXNRD2 and PRDX1 in HUVEC." (PMID 24093550, 2013).
malaise (1 paper, 2021). A feeling of general discomfort or uneasiness, an out-of-sorts feeling. "In another family (TXNRD2), symptoms such as malaise were linked to PAI rather than being overlooked." (PMID 34258490, 2021).
metastatic disease (1 paper, 2016). "Our data confirmed high levels of TXNRD2 expression in biopsies of patients who later developed metastatic disease." (PMID 26573231, 2016). "Increased expression of TXNRD2 (mean intensity normalised to β-actin) was present in approximately 30% of biopsies from patients who developed metastatic disease within 5 years of the initial biopsy." (PMID 26573231, 2016). "The TXNRD2 gene was upregulated in patients who later progressed to metastatic disease but not in patients whose tumour remained localised." (PMID 26573231, 2016).
myeloma (1 paper, 2022). "As an ROS-detoxifying enzyme, TXNRD2 is critical for cellular redox homeostasis, and TXNRD2 deficiency can contribute to oxidative damage in myeloma cells, endothelium, and myocardial ischemia/reperfusion mice." (PMID 36569930, 2022).
pulmonary disease (1 paper, 2022). "Txnrd2 is a mitochondrial selenoenzyme, and we speculate that preservation of this enzyme may be important given the role of mitochondrial biology in neonatal pulmonary disease." (PMID 36552625, 2022).
Stroke (1 paper, 2008). Sudden impairment of blood flow to a part of the brain due to occlusion or rupture of an artery to the brain. "Our data imply that it is Txnrd1 and not Txnrd2 that plays a critical role in brain development, however this does not rule out any contribution of Txnrd2, for instance under pathological conditions such as stroke and trauma." (PMID 18350150, 2008).
cancer (22 papers, 2012 to 2025). A tumor composed of atypical neoplastic, often pleomorphic cells that invade other tissues. "As our mechanistic data suggests, GPx4 significantly contributes to HCC protection by selenium, even if other selenoproteins as SELP, DIO1 and TXNRD2 show similar positive association with cancer survival and may also be involved." (PMID 29515790, 2018). "Although inhibition of either xCT/GSH/GPX4 (by BSO) or xCT-cysteine/CoA/TXNRD2 (by PANKi) alone can be tolerated in cancer cells, their combination leads to synthetic lethality." (PMID 40694424, 2025). "TXNRD1 is a critical selenoprotein in cancer cells, and found to be overexpressed in several cancer types when compared to TXNRD2 and TXNRD3." (PMID 36358931, 2022). "The ubiquitously expression of GPX1,GPX4,TXNRD1 and TXNRD2 in humans has been reported in previous studies, and our study further confirmed these genes were also ubiquitously expressed in different types of cancer." (PMID 33706760, 2021). "The expression levels of the GPX1 and GPX3 genes were positively correlated with the stromal- and immune-cell scores, and the TXNRD2 gene was negatively correlated with the stromal-cell score for all but a few cancers." (PMID 33706760, 2021). "Overexpression of thioredoxin reductase 2 (TrxR2) in cancer cells is often considered a critical factor in the complex interplay of tumorigenesis, disease progression, and the resistance to apoptosis, underscoring its significant role in the intricate dynamics of cancer development and survival." (PMID 39839762, 2024). "The role of TXNRD3 in cancer development is less known than the role of TXNRD2." (PMID 36358931, 2022). "The association of SNPs in TXNRD1 and TXNRD2 with disease risk was only observed in advanced stage or high grade cancers and not in localized low-grade cases." (PMID 23133653, 2012). "This section will be focused on TXNRD1 as it has been the main TXNRD studied in cancer, and we will briefly comment on TXNRD2 and TXNRD3 and their relationship to cancer metabolism." (PMID 36358931, 2022). "The specific physiological role of TXNRD2 and TXNRD3 in cancer cells remains to be determined, with some recent studies starting to enlighten their role separately." (PMID 36358931, 2022). "Despite limited evidence, these findings intimate that TXNRD2 and TXNRD3 also inhibit oxidative stress via the thioredoxin system in cancers as TXNRD1, thereby promoting cancer cell resistance to cell death." (PMID 36358931, 2022). "Our study similarly found up-regulation in the TXNRD2 and TXNRD3 genes in various types of cancer, which was also correlated with a poor prognosis of immune-cell subtypes." (PMID 33706760, 2021). "Some genes were expressed at similar levels in different types of cancer, including GPX1, GPX4, TXNRD1, TXNRD2 and TXNRD3." (PMID 33706760, 2021). "It is currently unclear the involvement of TXNRD2 and TXNRD3 in cancer." (PMID 36358931, 2022). "Whether TXNRD2 and TXNRD3 can serve as promising cancer treatment targets requires further analysis of how these genes play a role in oxidative stress in different cancers." (PMID 33706760, 2021). "Another explanation is that several cancer cell types have higher levels of antioxidants, which could inhibit ROS toxicity; specifically, increased levels of superoxide dismutase (SOD-2) and thioredoxin reductase 2 (TRX-2) were observed in mitochondria from cancer tissue samples." (PMID 25478322, 2014).
tumor (15 papers, 2012 to 2025). "Moreover, the high levels of TXNRD2 expression seen at the interface between the stroma and the tumor are consistent with an ongoing wound response in tumor-associated stroma." (PMID 23762225, 2013). "Thioredoxin reductase-2 (TrxR2) is a key mitochondrial antioxidant enzyme and its inhibition can lead to mitochondrial oxidative stress and tumor cell dysfunction." (PMID 40225571, 2025). "For example, MitoCur-1 selectively increases ROS generation in HCC cells by inhibiting thioredoxin reductase 2 (TrxR2), which simultaneously suppresses mitochondrial respiration and glycolytic metabolism, disrupting tumor metabolic plasticity." (PMID 41515171, 2025). "The positive correlation between the TXNRD2 gene and RNAss means that this gene may play a role in tumor promotor." (PMID 33706760, 2021). "Several antioxidant genes, including TXNRD2, are inhibited by KLF9, thereby increasing reactive ROS levels, which negatively impact tumor development." (PMID 41301778, 2025). "Regarding the SELENOP level, TXNRD2 and TXNRD3 tumor tissue expression was negatively correlated (p = 0.037 and 0.045), while GPX1 had a higher expression in the normal tissue, p = 0.034." (PMID 30469315, 2018).
cardiovascular disease (2 papers, 2021). "Experimental studies have shown a role for a subset of redox-active selenoproteins, including GPx1, GPx3, GPx4, and Txnrd2, in protecting against complex cardiovascular diseases, in part, by attenuating the harmful effects of reactive oxygen species." (PMID 34579115, 2021).
neurodegenerative disease (2 papers, 2008 to 2025). A disorder of the central nervous system characterized by gradual and progressive loss of neural tissue and neurologic function. "Since oxidative stress has been linked with neurodegenerative disease, we studied the roles of thioredoxin reductases in brain using mice with nervous system (NS)-specific deletion of cytosolic (Txnrd1) and mitochondrial (Txnrd2) thioredoxin reductase." (PMID 18350150, 2008). "Small molecules that modulate CoA synthesis or mimic CoAlation on TXNRD2 could potentially be developed as ferroptosis inhibitors specifically targeting the redox status of mitochondria, especially for neurodegenerative diseases in which ferroptosis plays a pathogenic role." (PMID 40694424, 2025).
TXNRD2 also shares sentences with these, for which no sentence is quoted: epilepsy (3 papers); Tremor (3); myocardial infarction (2); open-angle glaucoma (2); rheumatoid arthritis (2); abdominal aortic aneurysm (1); adenocarcinoma (1); atherosclerosis (1); benign prostatic hyperplasia (1); diabetic cardiomyopathy (1); endothelial dysfunction (1); exfoliation syndrome (1); gastric cancer (1); Hepatic fibrosis (1); hepatocellular carcinoma (1); hereditary cardiomyopathy (1); Huntington disease (1); Hypertension (1); infarction (1); Intellectual disability (1); Kashin-Beck disease (1); lung adenocarcinoma (1); lymphoma (1); melanoma (1); metabolic disease (1); myocardial ischemia (1); Obesity (1); omphalocele (1); pancreatic cancer (1); Parkinsonism (1).
A further 4 diseases each share a sentence with TXNRD2 in 1 paper.